DNMT1 (DNA methyltransferase 1)
Diseases named in the same sentence as DNMT1 in open-access papers (continued):
Sharing a sentence is not in itself a finding about the gene and the disease.
glioma (continued). "The levels of invasion and migration of glioma cells peaked in the double-negative control group, reached their lowest in the NUP37-depleted group, and were elevated in both DNMT1-overexpressing groups when compared to the NUP37-depleted group." (PMID 39174498, 2024). "Similarly, the OrisTM Wound Healing Assay findings revealed that the migration level of glioma cells was greatest in the double-negative control group, least in the NUP37-depleted group, and higher in both DNMT1-overexpressing groups compared to the NUP37-depleted group." (PMID 39174498, 2024). "The disruption of the Dnmt1/PCNA interactions is also confirmed by the use of a proximity ligation in situ assay (P-LISA) and the significant reduction of the Dnmt1/PCNA interactions in U251 cells (a glioma cell line) compared with Astro#40 cells (a non-tumor glial cell lines) (p = 0.003)." (PMID 20613874, 2010).
pancreatic cancer (81 papers, 2006 to 2025). "The overexpression of DNMT1 has been implicated in multiple cancers, including pancreatic cancer, where it shapes an epigenetic landscape that favors tumor growth and metastasis." (PMID 40387566, 2025). "Accordingly, restoration of miR‐148a resulted in the reactivation of TSGs, including p16, preproenkephalin and Ras association domain family member 1 in the AsPC‐1 pancreatic cancer cell line by specifically targeting DNMT1." (PMID 40387409, 2025). "In pancreatic cancer, increased expression of DNMT1 and aberrant methylation of promoters implicated in the downregulation of KLF4 expression result in impaired differentiation and unfavourable outcomes." (PMID 40387409, 2025). "DNMT1 was found to interact with menin, which is frequently mutated in pancreatic neuroendocrine tumors, and reversibly regulates pancreatic cancer cell growth." (PMID 27999365, 2016). "DNMT1 expression was upregulated in pancreatic cancer cells, possibly associated with the progression of disease symptoms in pancreatic carcinoma." (PMID 22455563, 2012). "Therefore, in pancreatic cancer cells, the modulation of miR‐377, specifically by targeting DNMT1, can potentially diminish DNA methylation levels associated with specific TSGs, thereby facilitating the reinstatement of their expression." (PMID 40387409, 2025). "Interestingly, loss of DNMT1 lowered the methylation level of the miR-34a promoter and elevated the miR-34a expression in pancreatic cancer cells." (PMID 34783292, 2021). "We found an association between high tumor expression of DNMT1 and shorter OS, concordant with previous studies in which high expression of DNMT1 was associated with poor prognosis in malignant lymphoma, renal cell carcinoma, pancreatic cancer, and bladder cancer." (PMID 27071379, 2016). "An inverse correlation is observed between the expression levels of DNMT1 and miR‐34a in individuals diagnosed with pancreatic cancer." (PMID 40387409, 2025). "A reciprocal relationship exists between miR‐377 and DNMT1 in pancreatic cancer cells, where DNMT1‐mediated promoter methylation significantly influences miR‐377 expression, while DNMT1 itself functions as a downstream target of miR‐377." (PMID 40387409, 2025). "Together, our findings demonstrate that the pharmacological inhibition of the G9a/DNMT1/UHRF1 complex enhances the cytotoxic response to conventional chemotherapeutic agents in pancreatic cancer cells." (PMID 39810240, 2025). "Building upon our previous characterization of Menin’s relationship with Dnmt1 in Hedgehog-mediated pancreatic cancer growth regulation, we investigated Menin’s role in PDAC metabolism." (PMID 40894906, 2025). "Next, we investigated the expression of DNMT1 in 6 pancreatic cancer cell lines and 1 human pancreatic ductal epithelial cell line HPDE by qRT‐PCR and western blot." (PMID 40387566, 2025). "It was found that pancreatic cancer stem cells demonstrated hypermethylation via DNMT1 upregulation, and the suppression of DNMT1 in pancreatic stem cells reduced their self-renewal and in vivo tumorigenic potential." (PMID 38672671, 2024). "The DNMT1/RBL2/c-Myc axis is involved in the inhibitory effect of HOXB9 on pancreatic cancer cell proliferation by blocking cell cycle progression." (PMID 37301547, 2023). "HOXB9 inhibits the proliferation of pancreatic cancer cells by blocking cell cycle progression through the DNMT1/RBL2/c-Myc axis." (PMID 37301547, 2023). "In pancreatic cancer, almost 80% of cases show upregulation of DNMT1, leading to hypermethylation, which is considered the predominant and aberrant epigenetic alteration in pancreatic cancer." (PMID 37798621, 2023). "It has been shown that overexpression of DNMT1 leads to KLF4 promoter hypermethylation, which contributes to decreased expression and is associated with poor differentiation of pancreatic cancer." (PMID 37239940, 2023).
pancreatic cancer (continued). "The regulatory relationship between DNMT1 and miR-497 has also been previously explored, with results suggesting that DNMT1 mediates the methylation of miR-34a promoter and promotes the resistance of pancreatic cancer cells to molecular targeted drugs." (PMID 35255904, 2022). "Here, we showed that FBP1 translocated into the nucleus and bound to DNA (cytosine‐5)‐methyltransferase 1 (DNMT1) to modulate the sensitivity of pancreatic cancer cells to PARP inhibitors." (PMID 34854226, 2022). "Apart from that, DNMT1 is also known to mediate the methylation of miR-34a promoter to enhance chemoresistance of pancreatic cancer cells." (PMID 35255904, 2022). "In pancreatic cancer cell lines with low DNMT1 expression, the DNMT inhibitor decitabine depletes DNMT1 and exerts anti-tumor effects." (PMID 36048239, 2022). "The methylation regulator DNMT1 is hypermethylated and overexpressed in pancreatic cancer, which can be initiated by miR-148a and lead to proliferation and invasion of pancreatic cancer cells." (PMID 36684288, 2022). "In pancreatic cancer, C188-9 combined with decitabine treatment modulates DNA methyltransferase 1 and significantly reverses the hypermethylation status of tumor suppressor genes in pancreatic cancer." (PMID 36291659, 2022). "Recently, scholars have successively discovered MEK1/2 inhibition (MEKi), DNA methyltransferase 1 (DNMT1), and cytoskeleton-associated protein 4 (CKAP4) and other therapeutic targets for pancreatic cancer, but it still needs further clinical verification." (PMID 36505775, 2022). "Among the four DNA transmethylases, only DNMT1 and DNMT2 were associated with ANKRD55 expression in pancreatic cancer." (PMID 33827590, 2021). "Fundamental to DNA methylation is DNMT1 activity, which is often overexpressed in pancreatic cancer." (PMID 29927979, 2018). "For example, the hedgehog transcription factor Gli1 targets the epigenetic modifiers DNMT1 and DNMT3a, which are positive targets of oncogenic epigenetic pathways in pancreatic cancer." (PMID 30060755, 2018). "Negative correlation of acetyl-DNMT1 and DNMT1 was observed in differentiated neuronal cells and pancreatic cancer cells, and decrease of acetyl-DNMT1 was observed in pancreatic ductal adenocarcinoma." (PMID 25960197, 2015). "A recent study has also reported on the observation of a substantially decreased DNMT1 expression after Gli1 interference in pancreatic cancer cells." (PMID 26317501, 2015). "Iodine-125 seed irradiation at a dose of 4 Gy decreases the protein expression of DNMT1 and DNMT3b in SW-1990 human pancreatic cancer cells." (PMID 24223648, 2013). "In order to corroborate previous findings, we then analyzed PPARγ, DNMT1, and 3B mRNA levels in four different pancreatic cancer cell lines." (PMID 22919364, 2012). "In conclusion, we find that treatment with the DNMT1 inhibitor 5-aza-dC induces remarkably fewer genes in pancreatic CAFs than pancreatic cancer cells." (PMID 22984426, 2012). "According to recent experiments, there is mutual influence between miR‐148a and DNMT1, which could impact cellular proliferation and migration in pancreatic cancer cells." (PMID 40387409, 2025). "Thereby, targeting miR‐148a/DNMT1 could be a promising therapeutic strategy for managing pancreatic cancer." (PMID 40387409, 2025). "According to recent experimentation in pancreatic cancer, DNMT1 exerts repressive effects on miR‐34a expression while concurrently promoting the activation of the Notch pathway through mediation of the hypermethylation process targeting the miR‐34a promoter region." (PMID 40387409, 2025). "In addition, the IL-6/STAT3 signaling pathway can methylate the SOCS3 via DNMT1, leading to pancreatic cancer progression and metastasis." (PMID 39195299, 2024). "Moreover, a subsequent study revealed that nuclear FBP1 interacted with DNMT1 to sensitize pancreatic cancer cells to PARP inhibitors, and this effect was independent of the enzymatic activity of FBP1." (PMID 34854226, 2022).
pancreatic cancer (continued). "Therefore, our data suggested that DNMT1 was the binding partner of FBP1 in pancreatic cancer cells." (PMID 34854226, 2022). "In vitro studies have shown that 5-Aza-CdR, a DNA methyltransferase 1 (DNMT1) inhibitor, could induce cell death and apoptosis of pancreatic cancer cells by reactivation of RASSF1A and upregulation of Bax genes." (PMID 34876903, 2021). "And another report demonstrated that activated interleukin-6/Stat3 signaling could induce suppressor of cytokine signaling 3 (SOCS3) methylation via DNMT1, resulting in pancreatic cancer growth and metastasis." (PMID 28360411, 2017). "Moreover, immunohistochemistry result suggested the expressions of GLI1, DNMT1, and DNMT3a in pancreatic cancer tissues were higher than those in adjacent normal tissues." (PMID 24822169, 2014). "Moreover, the expression of DNMT1 protein increased with the development of pancreatic cancer from normal tissue to precancerous lesions (PanINs) and to cancer (PDAC)." (PMID 24822169, 2014). "Therefore, targeting STAT3 or DNMT1 might represent a potential strategy in the treatment of pancreatic cancer." (PMID 39195299, 2024). "It is reported that aberrant methylation can lead to pancreatic cancer, and overexpression of DNMT1 may be a crucial factor leading to the increased DNA methylation in cancer cells, resulting in abnormal activation of transcription and inhibition of protein degradation." (PMID 32751889, 2020). "Moreover, we tested whether these observations have potential biomedical relevance for the treatment of pancreatic cancer through an experimental therapeutic trial in genetically engineered mice using a pharmacological Dnmt1 inhibitor." (PMID 26617245, 2015). "In this manner, induction of the miR‐152/DNMT1/KLF4 signalling pathway through epigenetic mechanisms by dietary DIM leads to the differentiation and substantial growth suppression of pancreatic cancer cells." (PMID 40387409, 2025). "Our findings have established that DNMT1 represses the expression of CBX7 in pancreatic cancer, and that CBX7 contributes to the inhibition of pancreatic cancer progression." (PMID 40387566, 2025). "miR-377 enhances TFPI2 by downregulating DNA methyltransferase 1 (DNMT1), promoting apoptosis in pancreatic cancer." (PMID 40361374, 2025). "Transfection of miR-148b or miR-152 in pancreatic cancer cells reactivated tumor suppressor genes such as BNIP3, SPARC, PENK, and TFPI-2 by downregulating DNMT1." (PMID 36959680, 2023). "IL-6/STAT3 signaling can promote pancreatic cancer growth and metastasis, which induce suppressor of cytokine signaling 3 (SOCS3) methylation through DNA methyltransferase 1 (DNMT1)." (PMID 33406733, 2021). "Increased CXCR4 expression was achieved with the knock-down of DNA methyltransferase 1 (DNMT1) or DNA methyltransferase 3 beta (DNMT3B), or with the inhibition of DNA methylation by 5-aza-2-deoxycytidine (5-aza) in pancreatic cancer cells." (PMID 32110952, 2020). "This study aimed to investigate the effect of zebularine on p16INK4a, p14ARF, p15INK4b, and DNA methyltransferase 1 gene expression, cell growth inhibition, and apoptosis induction in HCC PLC/PRF5 and pancreatic cancer PA-TU-8902 cell lines." (PMID 33841535, 2020). "DNA methyl transferases (DNMTs) play a very important role in DNA methylation in cells and we observed that DNMT1, DNMT3A and DNMT3B are themselves differentially methylated in pancreatic cancer." (PMID 28423671, 2017). "Increased expression of DNMT1, DNMT3A and DNMT3B was reported in pancreatic cancer, suggesting their role in pancreatic cancer development." (PMID 27999365, 2016). "In this study we aimed to evaluate the expression of PPARγ, DNMT1, and DNMT3B and their correlation with clinical-pathological features in patients with pancreatic cancer (PC), and to define the effect of PPARγ activation on DNMTs expression in PC cell lines." (PMID 22919364, 2012).
pancreatic cancer (continued). "In the same line, 60% of pancreatic carcinomas were recently found to be hypermethylated at the BRCA1 gene and the number of methylated genes significantly correlated to DNMT1 protein overexpression." (PMID 17047656, 2006). "In summary, miRs that specifically target DNMT1 and modulate the methylation patterns of TSGs like BNIP3 and SPARC can potentially be utilised as a therapeutic approach for inducing apoptosis in pancreatic cancer cells and reducing their tumorigenic properties." (PMID 40387409, 2025). "In the same study, the authors showed that DIM significantly induced miR-152 expression, blocking DNMT1, its binding to KLF4 promoter, thus, activating KLF4 expression, and inhibiting cell growth in vitro and tumorigenesis in animal models of pancreatic cancer." (PMID 37239940, 2023). "Targeting IL-6 in acupuncture treatment of pancreatic cancer is a promising research direction, which may involve IL-6/STAT3 axis, DNMT1-induced SOCS3 methylation, NRP-1, etc." (PMID 36105933, 2022). "Furthermore, DNMT1 inhibition reduces KLF4 promoter DNA methylation and activates KLF4 expression in pancreatic cancer cells." (PMID 33596966, 2021). "In pancreatic cancer cells, USP7 regulation of DNMT1 stability is dependent on DNMT1 acetylation." (PMID 34572918, 2021). "Complementary knockdown experiments using 2 specific Nupr1 siRNAs to transfect pancreatic cancer cells (MiaPaCa2) decreased Dnmt1 mRNA levels (3.8 fold ± 0.7; p < 0.01), without affecting either Dnmt3a or Dnmt3b expression." (PMID 26617245, 2015). "DNMT1 and DNMT3a are regulated by GLI1 in pancreatic cancer." (PMID 24822169, 2014). "Zebularine is a highly stable hydrophilic DNA methylation inhibitor, which preferentially depletes DNA methyltransferase 1 (DNMT1), as demonstrated in bladder, prostate, lung, colon, and pancreatic carcinoma cell lines, often resulting in inhibition of cell proliferation and induction of apoptosis." (PMID 23336012, 2013). "Compared to pancreatic cancer cells, few genes are reactivated by DNMT1 inhibition in pancreatic CAFs suggesting these cells do not harbor many functionally important alterations in DNA methylation." (PMID 22984426, 2012). "Consequently, this upregulation hinders the expression of DNMT1 protein and its interaction with the promoter region of KLF4, resulting in a decrease in promoter DNA methylation and the activation of KLF4 expression within pancreatic cancer cells." (PMID 40387409, 2025). "In pancreatic cancer cell lines, the suppression of KEAP1 protein by promoter methylation was demonstrated to be correlated with Ubiquitin-like containing PHD and RING finger domains 1 (UHRF1) increased expression, a scaffold protein for DNA methyltransferase 1 (DNMT1)." (PMID 32971994, 2020). "Two pancreatic cancer cell lines, PANC-1 (poorly differentiated, high level of Vimentin and low level of E-cadherin) and Capan-1 (well-differentiated, high level of E-cadherin and low level of Vimentin), were used to investigate the correlation between acetyl-DNMT1 and DNMT1 in vivo." (PMID 25960197, 2015). "Our data put in evidence important differences in the periodicity and in the phase relationships of PPARG, DNMT1, and DNMT3B expression levels among the diverse cell lines examined, maybe related to a different genetic background in the diverse pancreatic cancer cells." (PMID 22966223, 2012).